TSPO (translocator protein)
Diseases named in the same sentence as TSPO in open-access papers (continued):
Sharing a sentence is not in itself a finding about the gene and the disease.
Alzheimer disease (continued). "It should be noted that an increased content of TSPO was found in tissues and cells in a whole range of diseases of various etiologies, in particular, cancers of various organs, aging, Alzheimer’s disease, and heart diseases." (PMID 36290741, 2022). "The first-generation radioligand [11C]PK-11195 was reported to lead to higher TSPO PET signals in the brains of patients with amyotrophic lateral sclerosis, Alzheimer’s disease, Parkinson’s disease or individuals at risk of Huntington’s disease compared to healthy controls." (PMID 33725191, 2021). "The evaluation of TSPO density is now well-recognized as a relevant index of microglial activation and a great number of literature data have to date reported an upregulation of this biomarker in Alzheimer’s disease." (PMID 35069106, 2021). "High expression of TSPO in activated microglia has been reported in several neurodegenerative diseases, including Alzheimer’s disease, Huntington’s disease, ischemic stroke, multiple sclerosis and epilepsy, which indicates TSPO plays essential roles in the progression of these diseases." (PMID 33725191, 2021). "Future studies will be necessary to determine whether loss of neurons and/or blunted neuronal activity may contribute to reduced TSPO expression occurring in a substantial portion of patients with late-stage Alzheimer’s disease or Lewy body dementia." (PMID 32398717, 2021). "This approach has also been used in various publications related to TSPO in Alzheimer’s disease." (PMID 32839410, 2020). "Post-mortem studies suggest, however, that the major TSPO signal comes from microglia in Alzheimer’s disease, but we acknowledge that some of the signal may also reflect activation of astrocytes." (PMID 32375809, 2020). "Estimations of BP were also used to measure TSPO in Alzheimer’s disease." (PMID 32839410, 2020). "Although most animal studies conclude that TSPO increases in brain regions in Alzheimer’s disease animal models, it is important to note that methodological issues inherent to small animal imaging may have influenced the results." (PMID 32839410, 2020). "And 318 healthy controls, confirmed the presence of an increase in TSPO in Alzheimer’s disease." (PMID 32839410, 2020). "Alzheimer’s disease has been the most widely assessed with more than forty preclinical and clinical studies, showing overall that TSPO is upregulated in this condition, despite differences in the topography of this increase, its time-course and the associated cell types." (PMID 32839410, 2020). "Thus, Alzheimer’s disease is the pathology of choice to compare the results obtained between different studies: Is TSPO modified?" (PMID 32839410, 2020). "At sites of injury, inflammation, and neuropathological conditions (stroke, Alzheimer’s disease, Parkinson’s disease, Huntington’s disease, multiple sclerosis, and amyotrophic lateral sclerosis), TSPO expression was robustly enhanced in reactive microglia and astrocytes." (PMID 29506545, 2018). "Consequently, TSPO overexpression has been confirmed in Alzheimer's disease (AD), multiple sclerosis, stroke, Parkinson's disease, HIV encephalitis, and trauma." (PMID 26199457, 2015). "Thus, TSPO intensity is increased in Alzheimer’s disease (AD), stroke, and multiple sclerosis (MS), making imaging TSPO ligands an important system for diagnosing neurodegenerative diseases." (PMID 24977274, 2014). "It is possible that the expected loss of function in TREM2 conferred by p.R47H may underlie the lower levels of TSPO signal seen in the TREM2 p.R47H carriers and that this reduced microglial activation may be a factor in the increased risk of Alzheimer’s disease in these carriers." (PMID 37990275, 2023). "Additionally, a multi-tracer study longitudinally tracking microglial activation and glucose hypometabolism simultaneously in a transgenic mouse model of Alzheimer’s disease observed discrepancies between the data trend of the TSPO-tracer [18F]GE-180 and [18F]FDG." (PMID 37108685, 2023).
Alzheimer disease (continued). "For example, we recently showed that in the frontal cortex of Alzheimer’s disease subjects, the most frequent neurodegenerative disease, both astrocytes and microglia overexpress TSPO, and TSPO increase in astrocytes could even appear earlier than in microglia." (PMID 37408083, 2023). "Furthermore, TSPO expression was also found upregulated in several inflammatory and neurodegenerative diseases, such as Alzheimer’s disease, Parkinson’s disease, and pediatric autoimmune neuropsychiatric disorders associated with streptococcal infection (PANDAS)." (PMID 35606817, 2022). "Since TSPO expression can also be expressed by astrocytes, and astrocytic TSPO levels increase before microglial TSPO in Alzheimer’s disease, it is plausible that astrocytes are the primary source of cortical TSPO in people with schizophrenia and elevated inflammation." (PMID 35844224, 2022). "In a previous study, the TSPO alterations were investigated in the advanced Alzheimer disease (AD), dementia with Lewy bodies (DLB) and Parkinson disease dementia (PDD) brains via quantitative autoradiography using [3H]PBR28 as the radioligand." (PMID 34572554, 2021). "Translocator protein 18 kDa (TSPO), expressed in the outer membrane of mitochondria, is a reliable inflammatory biomarker and related to many human diseases, including metastatic cancer, inflammatory and neurological diseases (such as Alzheimer’s disease and Parkinson’s disease)." (PMID 32902340, 2020). "In all cases, 11C-(R)-PK11195 was used as a translocator protein (TSPO) binding to mitochondrial peripheral benzodiazepine sites upregulated in microglia and other mononuclear phagocytes in response to proinflammatory stimuli or in neurodegenerative conditions such as Alzheimer’s disease." (PMID 32241286, 2020). "Finally, the very use of the cerebellum in the SUVR method as a (pseudo-)reference region could be questioned given the presence of an upregulation of TSPO in this region between Alzheimer’s disease patients and healthy control subjects." (PMID 32839410, 2020). "Additionally, in Alzheimer’s Disease (AD), most TSPO-positive cells were also Iba1-positive." (PMID 31963507, 2020). "CB2 activation is considered to relate to the neuroprotective responses that may occur predominantly in the early stage of brain disorders such as Alzheimer’s disease, while an increase in TSPO expression tends to occur later during neuroinflammation, in a proinflammatory fashion." (PMID 31707986, 2019). "Translocator protein (TSPO) is a mitochondrial protein expressed by microglia, ligands for which are used as a marker of neuroinflammation in PET studies of Alzheimer’s disease (AD)." (PMID 39540994, 2024). "We analyzed 85 patients with PET/MR imaging for microglial activation (TSPO, [18F]DPA-714) and Aβ ([18F]AV-45) within the prospective Alzheimer’s Disease Immunization and Microbiota Initiative Study Cohort (ADIMIC)." (PMID 37801139, 2024). "In the brain, increased TSPO PET signal is detected in neuroinflammatory and neurodegenerative diseases such as multiple sclerosis (MS) and Alzheimer’s disease." (PMID 37516868, 2023). "In this study we compared the recently developed TSPO tracer [18F]F-DPA, with [18F]DPA-714 and [11C]PBR28 by performing in vivo PET imaging on the same Alzheimer’s disease mouse model APP/PS1-21 (TG) and wild-type (WT) mice with all three radiotracers." (PMID 34542805, 2022). "TSPO PET studies have been conducted and showed an increase in TSPO signal in patients with Alzheimer disease, Parkinson disease, and multiple sclerosis." (PMID 29875332, 2018). "Upregulated translator protein (TSPO) has been imaged using positron emission tomography in patients with mild cognitive impairment (MCI) and Alzheimer's disease." (PMID 25329999, 2014).
Alzheimer disease (continued). "The use of translocator protein (TSPO) radioligands and positron emission tomography (PET) scans are the current method to image neuroinflammation in living patients with neurological conditions such as Alzheimer’s disease (AD)." (PMID 39540994, 2024). "In Alzheimer’s disease (AD), the cerebellum is the pseudo-reference region for comparison with the cerebral cortex due to the absence of AD pathology and lower levels of TSPO." (PMID 37580767, 2023). "Longitudinal in vivo study in the 5xFAD mouse model shows that TSPO and oxidative stress assessment through [18F]DPA-714 and [18F]FSPG-PET imaging, respectively, could serve as a potential tool for the evaluation of Alzheimer disease progression." (PMID 35676734, 2022). "The translocator protein (TSPO) has been identified as a positron emission tomography (PET)-visible biomarker of inflammation and promising immunotherapeutic target for the treatment of Alzheimer’s disease (AD)." (PMID 33740987, 2021). "Similarly, in another set of TSPO PET images, the choice of the quantification approach greatly impacted the statistical significance of the TSPO alteration in Alzheimer’s disease." (PMID 32839410, 2020). "For example, in the hippocampus, one of the regions most involved in Alzheimer’s disease, there is no consensus on the presence of TSPO overexpression." (PMID 32839410, 2020). "TSPO has been shown to be a robust and sensitive biomarker for microglial activation in neurodegenerative conditions and increased TSPO levels in PET were found in the progression of mild cognitive impairment and Alzheimer’s disease." (PMID 31963507, 2020). "In neurodegenerative diseases, such as Alzheimer’s disease (AD), activated microglia are detected by histological analyses of postmortem human brains and positron emission tomography (PET) imaging using TSPO (Translocator protein) ligands in living patients." (PMID 30558641, 2018). "Consequently, TSPO has been identified as an in vivo biomarker of neuroinflammation detectable via positron emission tomography (PET) and a potential target for the treatment of a range of neurodegenerative diseases, including Alzheimer's disease 3-5." (PMID 40225565, 2025). "Finally, it has recently been found that the variable cortical burden of TSPO does not correlate with the burden of activated microglia or reactive astrocytes in the brains of late-stage Alzheimer’s disease patients." (PMID 32398717, 2021). "Finally, the cell body regions of DA neurons (VTA and substantia nigra parscompacta) show TSPO increases in the absence of amyloid plaques, thus confirmingthe inflammation observed in the midbrain of a mouse Alzheimer’s disease model." (PMID 34286270, 2021). "Many excellent narrative reviews on TSPO PET have been published these last few years, and dozens of critical literature reviews covered more or less extensively this topic in the main diseases with neuroinflammatory component, like Alzheimer’s disease or multiple sclerosis." (PMID 34387719, 2021). "The mitochondrial translocator protein (TSPO) has been identified as an in vivo biomarker of neuroinflammation detectable via positron emission tomography (PET), and a potential immunotherapy target for the treatment of a range of neurodegenerative diseases including Alzheimer’s disease (AD)." (PMID 33740987, 2021). "Interestingly, when we measured the binding of TSPO on the whole tissue (i.e., before cell sorting), we were not able to observe any TSPO increase in Alzheimer’s disease in the frontal cortex." (PMID 32839410, 2020). "With regard to neurodegenerative diseases, in a rodent model of Alzheimer’s disease (AD), e.g., the SAMP8 mouse, 500 mg/kg of curcumin in a five month diet increased HO-1 gene expression, together with regulators of mitochondrial function, e.g., the translocator protein (TSPO)." (PMID 31100781, 2019).
Alzheimer disease (continued). "In the past, the TSPO radiotracer ligand [11C]PK11195 was successfully applied to depict glial activation in various CNS diseases like multiple sclerosis, Huntington’s disease, amyotrophic lateral sclerosis, Alzheimer’s disease, traumatic brain injury, and ischemic stroke." (PMID 29312111, 2017).
glioma (87 papers, 2011 to 2026). A benign or malignant brain and spinal cord tumor that arises from glial cells (astrocytes, oligodendrocytes, ependymal cells). "This probe revealed the high TSPO expression in HLA-DR+ glioma-associated myeloid cells, including CD45medCD14+++ MDSCs and CD45highCD14++ TAMs." (PMID 39770505, 2024). "On the other hand, TSPO is recognized as an imaging target for glioma-associated inflammation and reactive astrogliosis." (PMID 38255293, 2024). "Tumor-associated macrophages (TAMs) and microglia are the main cell entities of the TME for the imaging of glioma-associated inflammation, as both cell types show high upregulation in expression of the translocator protein (18 kDa) (TSPO) upon activation." (PMID 38255293, 2024). "We found that TSPO expression is associated with prognostically unfavorable glioma phenotypes and that TSPO promotor hypermethylation is linked to IDH mutation." (PMID 37697350, 2023). "Some studies compared the diagnostic performance of TSPO PET in gliomas with respect to that of other imaging modalities (MRI or amino-acid PET)." (PMID 37238297, 2023). "We therefore evaluated TSPO enrichment/expression in connection with its underlying histopathological and molecular features in gliomas." (PMID 37697350, 2023). "On the contrary, TSPO deficiency increased the apoptotic rate of GL261 mouse glioma cells as measured by elevated basal caspase-3 activity, a phenotype which we also observed in TSPO-deficient BTICs." (PMID 37158962, 2023). "Recently, we found a TSPO PET signal to be associated with survival in patients with recurrent glioma." (PMID 37536737, 2023). "It is still a matter of debate to what proportion TSPO expression in glioma is related to tumor cells and to inflammatory cells such as glioma-associated microglia/macrophages (GAM)." (PMID 35453488, 2022). "Immunohistochemistry (IHC) validated the reduction in tumor volumes and further revealed the presence of reactive TSPO-expressing glioma-associated microglia/macrophages (GAMMs) in the TME." (PMID 33500706, 2021). "For this purpose we measured at early time after treatment the uptake of [18F]FLT and [18F]VC701 radiopharmaceuticals targeting thymidine kinase 1 (TK1) and Translocator Protein 18 kDa (TSPO) which are receptors associated with glioma malignancy." (PMID 34012924, 2021). "TSPO knockdown of glioma C6 cells increased the association of mtCNPase with all Complexes 1.5- to 2.8-fold." (PMID 32370072, 2020). "Several lines of evidence indicate that TSPO plays a functional part in glioma hallmark features such as resistance to apoptosis, invasiveness, and proliferation." (PMID 33066460, 2020). "In this perspective, it might be plausible hypothesizing TSPO as a hallmark of glioma aggressiveness and propensity to evolve towards an anaplastic form." (PMID 37238297, 2023). "Glioma-associated microglia/macrophages (GAMs) are the main glial cells that may impact TSPO expression distribution after activation." (PMID 36293329, 2022). "A better knowledge of the TSPO expression sources and the underlying TSPO dynamics upon therapy will be crucial in order to improve our understanding of in vivo TSPO-targeted imaging in gliomas." (PMID 33500706, 2021). "Moreover, TSPO expression can correlate with glioma tumor grade in certain settings and has been linked with disease progression and diminished survival." (PMID 26517124, 2015). "Since TSPO is enriched in glioma, it may be a diagnostic biomarker." (PMID 36278207, 2022). "IHC analyses revealed, in concordance to the ARG findings, TSPO-labelled astrocytes and neuroinflammatory cells beyond the glioma margin while LAT1 was only highly expressed within the tumor." (PMID 38255293, 2024). "Out of those, 119 were initial diagnoses, comprising 56 patients with newly diagnosed glioblastoma WHO 4 and 11 patients with newly diagnosed glioma WHO 2 at the time of TSPO-PET." (PMID 39150564, 2024).
glioma (continued). "In line with our findings in glioma, there is also evidence of ipsilateral and contralateral elevation of TSPO in epilepsy, likely representing neuroinflammation." (PMID 39150564, 2024). "TSPO is overexpressed in activated microglia and macrophages, and its expression has been reported to be upregulated in gliomas." (PMID 38730666, 2024). "Overall, these results highlighted 32 as a promising PET ligand for evaluating TSPO expression in glioma." (PMID 39275061, 2024). "Eighty-seven glioma patients at initial diagnosis who underwent PET targeting the translocator protein (TSPO) using [18F]GE-180, dynamic amino acid PET using [18F]FET, and T1-/T2-weighted MRI scans were examined." (PMID 38396261, 2024). "For instance, the 3rd generation TSPO radioligand [18F]GE-180 has shown promising results in preclinical studies performed on rodents and in human glioma PET studies." (PMID 38255293, 2024). "Our aim was to provide a comprehensive overview of the existing literature concerning the clinical applications of positron emission computed tomography (PET) with radiopharmaceuticals targeting the translocator protein (TSPO) in gliomas." (PMID 37238297, 2023). "In particular, the authors correlated the results of TSPO PET/MRI performed by employing the second-generation tracer [18F]-DPA-714 with in-depth immunophenotyping carried out in specimens obtained from glioma stereotactic biopsies." (PMID 37238297, 2023). "In this setting, transcription factor binding to an unmethylated TSPO promotor most likely explains the overexpression of TSPO in IDH-wildtype gliomas." (PMID 37697350, 2023). "used a dual-tracer TSPO and FET approach to image glioma-associated microglia and macrophage dynamics under immunomodulating treatment." (PMID 37536737, 2023). "Further studies are warranted and will enhance the evaluation of TSPO PET for prognostication in glioma patients." (PMID 37536737, 2023). "We thoroughly tested the monoclonal TSPO antibody with western blot experiments on transient TSPO-knockdown glioma cells, on glioma cells with an antibody epitope blocking approach and on protein lysates from 4 different cryo-conserved GBM samples." (PMID 37697350, 2023). "The TSPO expression in gliomas has already been evaluated using positron emission tomography and single photon emission computed tomography (SPECT)." (PMID 36831378, 2023). "We performed direct bisulfite sequencing of nearly the complete TSPO promotor CpG island region (72 of 80 single CpGs covered) within 22 human glioma samples (10 IDH-mutant and 12 IDH-wildtype)." (PMID 37697350, 2023). "We employed in silico queries from the TCGA Research Network and compared the normalized expression values (RPKMs) of TSPO among IDH-mutant/-wildtype gliomas across reported WHO grades, and across glioblastoma (GBM) transcriptional subtypes." (PMID 37697350, 2023). "More specifically, TSPO expression is higher in IDH wildtype compared to IDH-mutant gliomas (WHO grade 4)." (PMID 37158962, 2023). "These last findings suggest a complementary role of the two PET imaging modalities (TSPO and amino-acid) for glioma characterization and are in agreement with previously published preclinical data." (PMID 37238297, 2023). "On the other hand, aside from being overexpressed on activated microglia, an increased TSPO expression has been reported on glioma tumor cells, with a positive correlation with tumor grade and biological aggressiveness." (PMID 37238297, 2023). "Another relevant issue is represented by the role of TSPO PET with respect to amino-acid PET in the different clinical settings of glioma patients (diagnosis, recurrence, radiotherapy planning)." (PMID 37238297, 2023). "To analyze a potential epigenetic regulation mechanism of TSPO expression we analyzed in silico open-access data of Illumina K450 methylation arrays from different glioma types (TCGA-LGG and TCGA-GBM)." (PMID 37697350, 2023).